CFTR (CF transmembrane conductance regulator)
Diseases named in the same sentence as CFTR in open-access papers (continued):
Sharing a sentence is not in itself a finding about the gene and the disease.
tumor (continued). "At the germline level, two missense mutations predicted to be likely pathogenic were found in compound heterozygosity affecting the Cystic Fibrosis gene CFTR that has been recently classified as a tumor suppressor gene, whose dysregulation represents a severe risk factor for developing CRC." (PMID 37046605, 2023). "Indeed, CFTR’s action as a tumor suppressor in the GI tract is considered strongest in the intestine." (PMID 35743652, 2022). "Given its role as a tumor suppressor, strategies which could upregulate or restore CFTR activity in tumor cells could prove to be immensely beneficial in the clinic." (PMID 35743652, 2022). "Finally, CFTR has been reported to regulate the expression of MUC4, a glycoprotein implicated in tumor progression." (PMID 35743652, 2022). "Furthermore, inhibition of CFTR inhibition in vivo suppressed xenograft tumor development, pinpointing CFTR as a potential biomarker in OC." (PMID 33562306, 2021). "Supporting this, KCNQ1, CFTR and ClCN-2 have been described as tumor suppressors in CRC." (PMID 33117152, 2020). "CFTR has been reported as an important tumor suppressor gene by inhibiting autophagy." (PMID 33123317, 2020). "However, later experiments showed that CFTR is closely related to classical tumor biomarker carbohydrate antigen 199 (CA199) in GC, and CFTR expression increases with age and is associated with the clinical stage of GC." (PMID 32104192, 2020). "Taken together, these novel findings strongly suggest CFTR could be an effective tumor suppressor in HNC." (PMID 32182826, 2020). "CFTR silencing also altered mRNA expression levels of other tumor-related genes." (PMID 32182826, 2020). "It is interesting to note that the expression of all of the major ion transporters involved in colonic transepithelial Cl- secretion show sexual dimorphism and are modulated by estrogen and the estrous cycle in the female, including CFTR a known tumor suppressor." (PMID 33363037, 2020). "A primary tumor was judged CFTR positive if a minimum of 10% of epithelial cells were stained." (PMID 31191661, 2019). "Data suggests that CFTR may play a role in tumor resistance to chemotherapy." (PMID 41147257, 2025). "Furthermore, several studies suggest that CFTR itself functions as a tumor suppression gene." (PMID 40066329, 2025). "Moreover, CFTR dysfunction may impact immune responses, influencing the infiltration and activation of immune cells within the tumor microenvironment." (PMID 37686519, 2023). "Interestingly, the CFTR inhibitor miR-145-5p is a recognized tumor suppressor miRNA." (PMID 37104011, 2023). "However, the Annexin-A2 complex affects chloride ion flux via CFTR, and could therefore lead to tumor development." (PMID 37408210, 2023). "Although the mechanism of CFTR tumor suppression is not well established, several mechanisms including dysregulation of Wnt/β-catenin signaling and epithelial barrier damage induced pro-inflammatory signaling have been discovered that could explain CFTR’s tumor-suppressive role." (PMID 35626748, 2022). "More concrete evidence for a role of CFTR in more advanced EMT (Type 3) has been established by studies on the role of CFTR as a tumour suppressor, some authors suggesting a direct (causal) link between the downregulation of CFTR in tumour cells and EMT induction." (PMID 32365523, 2020). "Interestingly, CFTR has also recently been proposed as a tumour suppressor protein." (PMID 30764828, 2019). "Thus, the current study indicates that CFTR, as demonstrated to play an important role in tumor migration and invasion, may be used as a potential prognostic indicator in NPC." (PMID 27769067, 2016). "In addition, CFTR was a chloride channel and the cause of cystic fibrosis; DHX57 was a putative ATP-dependent RNA helicase truncated in this TCC tumor; and ASTN1 was a neuronal adhesion molecule shown to be mutant in previous tumor studies." (PMID 23587365, 2012).
tumor (continued). "Upon binding, inh‐2 stabilizes CFTR, preventing RNF5 from recognizing and ubiquitylating it, and has shown promising anti‐tumor activity in preclinical studies by inhibiting tumor growth and promoting apoptosis in various cancer models." (PMID 39021054, 2024). "CFTR deficiency as measured by low mRNA and protein expression levels, which may be caused by RAS, PKC, and IFNα signaling or epigenetic silencing, is correlated with CRC tumorigenesis and metastasis, suggesting that CFTR has an active tumor suppression role in the colon." (PMID 35626748, 2022). "The relationship between CFTR and EMT (reviewed elsewhere) has been suggested based on a direct link between the down-regulation of CFTR in CF or tumor cells and EMT induction." (PMID 35500936, 2022). "CFTR has also been shown to be involved in the regulation of various downstream signaling pathways, including NF-κB and ERK in tumor cells." (PMID 35743652, 2022). "On the other hand, this work also sheds some light on the role of CFTR as a protector of EMT and tumour suppressor, which can lead to novel avenues in the treatment/prevention of carcinogenesis." (PMID 33106471, 2020). "Apart from WDR1, several other oncoproteins and tumour suppressors, such as LDHA, CLIC1, ARPC5, ZYX, RCN1, FHIT and CFTR, were identified in this study." (PMID 32601462, 2020). "Apart from that, the regulatory effect of CFTR on PI3K/Akt pathway is validated in our xenograft model, which showed up‐regulation of Akt and p‐Akt in CFTR‐overexpressing tumours compared to control tumours." (PMID 32463592, 2020). "In only one case (DD439), a signal for CFTR and KRT81 was seen in immunohistochemical stainings of the primary tumor, whereas the corresponding organoid line only showed a high KRT81 expression on protein and mRNA level." (PMID 31191661, 2019). "There is also strong evidence that CFTR acts as a tumor suppressor in sporadic, non-CF CRC, lacking germline CFTR mutations." (PMID 35743652, 2022). "To examine whether miR-125b targets CFTR and CGN in human CRC, we analyzed the expression patterns of CFTR and CGN in the tissue microarray containing tumor-adjacent normal tissues, primary CRC tissues and distant metastatic tissues." (PMID 34830864, 2021). "However, another finding demonstrates that CFTR activation inhibits GBM cell proliferation and migration, indicating that CFTR functions as a tumor suppressor in GBM." (PMID 34046412, 2021). "CFTR serves as a pivotal tumor suppressor through complex mechanisms; CGN, another downregulated gene, is located in the cytoplasmic face of tight junctions and plays an indispensable role in tumor cell polarization, proliferation and migration." (PMID 34830864, 2021). "In a second cohort, CFTR protein expression was lower in tumor vs. normal tissue and CFTR mRNA expression was reduced in metastatic vs. non-metastatic tumors." (PMID 33363037, 2020). "In addition, it was confirmed, by immunohistochemical analysis, that both CFTR and KRT81 were preserved in 6 out of 7 tumors, indicating that the organoids had the same subtype as their primary tumor." (PMID 33178018, 2020). "To answer the question if PDAC organoids express the same subtype-specific immunoreactivity as their corresponding primary tumor, we performed immunohistochemical stainings for KRT81 and CFTR on paraffin sections for all patients of which organoids were derived from resection specimens (n = 7)." (PMID 31191661, 2019). "Exocrine like- Increased expression of tumor cell-derived digestive enzyme genes, e.g. Islet-derived 1 beta (REG1B), pancreatic lipase-related protein 2 (PNLIPRP2), and cystic fibrosis transmembrane conductance regulator (CFTR)." (PMID 29928492, 2018).
tumor (continued). "Among all the studied channels, only CFTR has lower expression in cancer cell lines compared to normal cells, while Kv1.3, Kv7.1, and TASK-1 were downregulated in PDAC tissue compared to healthy tissue, suggesting a protective role and tumor suppressive function for these channels." (PMID 33178018, 2020). "However, when both drugs were combined significant additive effects were observed in both control and CFTR knock-down cells, suggesting that CFTR potentiation might be a promising strategy for adjuvant therapy irrespective of tumor CFTR expression levels." (PMID 35715537, 2022). "Notably, CFTR also acts as a tumor suppressor in several major non-GI tract cancers." (PMID 35743652, 2022).
bacterial infection (67 papers, 2010 to 2025). "It was found that CFTR such as elexacaftor, tezacaftor, and ivacaftor helped to lessen bacterial infections and other illnesses linked to CF to some extent." (PMID 41044511, 2025). "To assess how CFTR loss of function in macrophages affects lung defense against bacterial infection, we intratracheally challenged the Mac-CF and Ctrl mice with PsA (2.0x107 CFU)." (PMID 38035088, 2023). "The loss of CFTR function in pulmonary epithelial cells causes surface dehydration, mucus build‐up, inflammation, and bacterial infections that lead to lung failure." (PMID 34382377, 2021). "Loss-of-function mutations to the CFTR gene cause dehydrated mucus on the apical side of epithelial cells and increase the susceptibility of bacterial infection, especially in the airway and pulmonary tissues." (PMID 28805732, 2017). "In the lungs of CF patients, defective CFTR leads to production of thick mucus that obstructs airways and thus predisposes the patients to recurring bacterial infection." (PMID 25313718, 2014). "Recent studies also demonstrate the importance of CFTR function in CF airway host defense, wound repair and airway remodeling, with CFTR dysfunction implicated in excessive lung inflammation, bacterial infection and colonization." (PMID 24056672, 2013). "Moreover, recent studies verify that dysfunctional CFTR (mutation/acquired) impairs bacterial clearance by macrophages that increase susceptibility to bacterial infections." (PMID 25794013, 2015). "Evidence shows that restoration of CFTR channel protein function is associated with improved mucociliary clearance, and airway surface hydration, enhancing endogenous defence mechanisms by influencing the microbiology and response to bacterial infections in CF airways." (PMID 38541936, 2024). "Induction of CFTR dysfunction in the absence of IAV leads to similar findings, and correction of CFTR function leads to correction of the pH of the ASL and reduced susceptibility to bacterial infections, supporting the hypothesis that CFTR is a central mediator of secondary bacterial infection." (PMID 37318849, 2023). "Thus, we investigated whether these CFTR polymorphisms suppress the proinflammatory response of airway epithelial cells to bacterial infection and CS exposure." (PMID 36768629, 2023). "Hence, the reduced uptake and binding of M. abscessus could be linked to CFTR deficiency, potentially resulting in the failure to trigger an effective immune response and ultimately rendering the host more susceptible to bacterial infection." (PMID 37762308, 2023). "Because bacterial infections tend to persist in most pwCF, even after CFTR modulator treatment, it is important to consider alternative models for modulator-related studies, but also consider their limitations." (PMID 40512037, 2025). "To further characterise the functional importance of EHF in AECs, we assayed key activities known to be impaired during pathological processes such as CFTR function, cilia motility, epithelial barrier integrity and response to bacterial infection." (PMID 40590703, 2025). "CFTR modulator therapies have positive clinical outcomes, yet chronic inflammation and bacterial infections persist in people with CF (pwCF)." (PMID 39935472, 2025). "Further studies are needed to fully understand the role of CFTR modulators in bacterial infections and contrast to AMR in individuals with FC." (PMID 38541936, 2024). "To establish the impact of bacterial infection on CFTR modulator PK, we exploited the mouse model of P. aeruginosa pneumonia and evaluated IVA concentrations in murine plasma, lung, and ELF." (PMID 36625583, 2023). "The increase in CFTR protein and function observed after 24 h of bacterial infection is consistent with our previous studies using supernatant of mucopurulent material (SMM) from the lungs of pwCF, which induced HBE inflammation." (PMID 37998353, 2023).
bacterial infection (continued). "Collectively, these findings highlight both the importance of CFTR function during infectious challenge and demonstrate a central role for the lung epithelium in secondary bacterial infections following IAV." (PMID 37318849, 2023). "More studies are needed to elucidate how pre-existing bacterial infection and inflammation affect the efficacy of CFTR-targeted therapies." (PMID 37998353, 2023). "The most recent findings of the effect of CFTR modulators on bacterial infection and the inflammatory process are also presented to provide critical hints towards the identification of relevant therapeutic targets to overcome the respiratory pathology of pwCF." (PMID 36902441, 2023). "Depletion of CFTR abundance mediated by miRNAs is further exacerbated by exposure to bacterial infection or proinflammatory cytokines, which augment expression of miRNAs that correspondingly inhibit CFTR transepithelial ion transport." (PMID 37168508, 2023). "Despite the clear benefits of CFTR modulators in pwCF, the impact on pre-existing bacterial infection appears limited and transitory." (PMID 37998353, 2023). "Here, we tested the impact of bacterial adaptation on the antimicrobial activity of CFTR modulators and that of bacterial infection on PK." (PMID 36625583, 2023). "The pathogenesis of the inflammatory response in CF can be derived either from the opportunistic bacterial infections or from intrinsic alterations of the inflammatory cells, following lack or dysfunction of CFTR." (PMID 35903151, 2022). "Despite novel pharmacotherapy restoring CFTR functionality being available, CF patients still suffer from bacterial infections." (PMID 34639158, 2021). "CFTR dysfunction deregulates fluid secretion in the lungs, which leads to thick mucus formation and recurrent bacterial infections." (PMID 33266084, 2020). "Although advances in CF knowledge and care (i.e., CFTR modulators) have improved clinical outcomes, patients with CF remain burdened by chronic, multi-drug-resistant bacterial infections." (PMID 30459435, 2018). "Briefly, RAW cells were treated with cigarette smoke extract (CSE), chloroquine (autophagy inhibitor), TFEB-shRNA, CFTR(inh)-172, and/or fisetin prior to bacterial infection for functional analysis." (PMID 29445254, 2017). "The most effective drugs for CF patients would ideally enhance F508del-CFTR Cl secretion and reduce the proinflamatory response to bacterial infection." (PMID 26018799, 2015). "In bronchial epithelial cells, adequate expression of the CFTR protein is required to prevent bacterial infection, which is the most common CF symptom." (PMID 23555857, 2013). "The further development of these and other models across species will be crucial to understanding CF pathophysiology (including the interplay between CFTR function and bacterial infection), and developing effective therapies for this disease." (PMID 23874438, 2013). "We suspect that considerable number of cases of bacterial infection would be gone unnoticed because of the enhanced CFTR-mediated HCO3− secretion upon bacterial infection." (PMID 21151921, 2010). "More importantly, the present study has also demonstrated the physiological significance of the CFTR-mediated prostatic HCO3− secretion in the host defense against bacterial infection." (PMID 21151921, 2010). "Therefore, understanding how CFTR dysfunction impairs the defense mechanisms of airway epithelia against bacterial infection is critical for exploring an effective treatment for CF." (PMID 38699141, 2024). "Clarifying the role of each CFTR functional defect in the development of CF lung disease may reveal the major routes responsible for the cycles of bacterial infection, inflammation and mucus accumulation in CF airways." (PMID 38699141, 2024). "In this context, CFTR dysfunction appeared to complexly disrupt normal lipid processing, worsening the chronic airway inflammation, and compromising the immune responses to bacterial infections." (PMID 39338347, 2024).